PRKN (parkin RBR E3 ubiquitin protein ligase)
Diseases named in the same sentence as PRKN in open-access papers (continued):
Sharing a sentence is not in itself a finding about the gene and the disease.
neurodegenerative disease (30 papers, 2013 to 2025). A disorder of the central nervous system characterized by gradual and progressive loss of neural tissue and neurologic function. "Mutation of genes linked to autophagic processes—for example, SQSTM1, optineurin/OPTN, E3 ubiquitin ligase PARKIN/PRKN, PINK1, TBK1—have also been implicated in many neurodegenerative diseases." (PMID 34944054, 2021). "PRKN, with MAPT, is the neurodegenerative disease-associated gene with the most abundant number of antisense genes and alternative antisense TSSs." (PMID 30610612, 2019). "About half of the neurodegenerative disease-associated genes, namely APP, PSEN1, and PSEN2 for AD; C9orf72 and MAPT for FTD and SNCA; and PRKN and PARK7 for PD, have larger number of DPI robust TSSs than annotated CAT CAGE clusters." (PMID 30610612, 2019). "Next, we combined the 833 participants in a single population set and compared the burden of protein-altering variants between T1R-affected vs T1R-free participants for PRKN, LRRK2, and 22 additional PD-linked genes included in the neurodegenerative disease panel." (PMID 41430073, 2025). "In the MM1 subtype, we found variants in genes involved in a heterogeneous group of molecular processes and neurodegenerative diseases, while in the VV2, we found an over-representation of genes involved in PD, such as HTRA2, PINK1, and PRKN." (PMID 36517866, 2022).
infection (8 papers, 2018 to 2025). The state of being infected such as from the introduction of a foreign agent such as serum, vaccine, antigenic substance or organism. "From this study, resistance and fluopyram nematicide application were both effective tools for managing PRKN abundances and infection in peanuts." (PMID 40264846, 2025). "The objective of this research was to: 1) evaluate effects of fungicides and PRKN-resistant cultivars on PRKN management, and 2) determine if infection by leaf spot pathogens increase PRKN disease in peanut production." (PMID 37849470, 2023). "Despite the fact that the IAV and secondary S. aureus infection induced PRKN-dependent mitophagy in cells, the influence of this kind of mitophagy on the pathogenesis of secondary infections was unknown." (PMID 40362402, 2025).
genetic diseases (3 papers, 2006 to 2024). "However, due to the increased speed and lowered cost of DNA sequencing, a growing number of individuals are being sequenced and diagnosed with PRKN-linked PD and other genetic diseases." (PMID 38767677, 2024).
kidney (2 papers, 2022 to 2024). "Conversely, knockout of PTEN-induced kinase 1 (PINK1), parkin RBR E3 ubiquitin protein ligase (PARK2), or BCL2-interacting protein 3 (BNIP3) inhibited mitophagy in TECs, which aggravated kidney injury." (PMID 35501332, 2022).
cardiovascular diseases (1 paper, 2023). "NT-proBNP was closely related in network 1 with PRKN, protein involved in autophagy and both were represented in most cardiovascular diseases." (PMID 36915695, 2023).
PRKN also shares sentences with these, for which no sentence is quoted: Alzheimer disease (18 papers); neurological disorders (13); Obesity (12); amyotrophic lateral sclerosis (8); hepatocellular carcinoma (8); acute kidney injury (7); autism spectrum disorder (7); frontotemporal dementia (7); ischemia (7); lung fibrosis (7); neurodevelopmental disorder (7); adenocarcinoma (6); Anxiety (6); Ataxia (6); Cerebral ischemia (6); movement disorder (6); osteosarcoma (6); heart failure (5); Intellectual disability (5); cholangiocarcinoma (4); epilepsy (4); esophageal squamous cell carcinoma (4); idiopathic pulmonary fibrosis (4); infectious disease (4); mitochondrial disease (4); adenoma (3); atherosclerosis (3); attention deficit-hyperactivity disorder (3); autosomal recessive disease (3); autosomal recessive juvenile Parkinson disease-2 (3).
A further 157 diseases each share a sentence with PRKN in 3 papers or fewer.